PFKFB3 (6-phosphofructo-2-kinase/fructose-2,6-biphosphatase 3)
Diseases named in the same sentence as PFKFB3 in open-access papers (continued):
Sharing a sentence is not in itself a finding about the gene and the disease.
osteosarcoma (6 papers, 2016 to 2025). A usually aggressive malignant bone-forming mesenchymal neoplasm, predominantly affecting adolescents and young adults. "ROCK2 promotes osteosarcoma growth and metastasis by modifying the PFKFB3 ubiquitination and degradation." (PMID 36775902, 2023). "The tumor suppressive effect of miR-26/PFKFB3 has been confirmed in osteosarcoma, in which miR-26b inhibits the proliferation and metastasis of osteosarcoma cells and stimulates cell apoptosis by inducing PFKFB3 downregulation." (PMID 36973739, 2023). "Since miR-26a was identified to inhibit invasion in osteosarcoma cells by targeting PFKFB3 and also target COX-2." (PMID 27833076, 2016). "Additionally, ROCK2 promoted osteosarcoma growth and metastasis by modulating the ubiquitination and degradation of PFKFB3." (PMID 40615369, 2025). "In addition to promoting angiogenesis in ECs, PFKFB3 and HK2 are also crucially involved in the progression of osteosarcoma by regulating aerobic glycolysis." (PMID 39252946, 2024). "Therefore, targeting glycolytic enzymes PFKFB3 and HK2 might be a promising therapy for osteosarcoma." (PMID 39252946, 2024).
preeclampsia (6 papers, 2019 to 2024). Preeclampsia is a hypertensive disorder of pregnancy that is characterized by new-onset hypertension with proteinuria presenting after 20 weeks of gestation, and depending on mild or severe forms may initially present with severe headache, visual disturbances, and hyperreflexia. "Expression levels of PFKFB3 and metastasis-associated lung adenocarcinoma transcript-1 (MALAT1) are reduced in placental tissues of early-onset preeclampsia patients." (PMID 39318551, 2024). "Collectively, the MALAT1/miR-26/PFKFB3 axis regulates EC angiogenesis by regulating glycolysis and plays a key role in the pathogenesis of early-onset preeclampsia." (PMID 39318551, 2024). "Knocking down MALAT1 can inhibit the expression of PFKFB3, thereby reducing glycolytic activity and ultimately leading to abnormal angiogenesis in early-onset preeclampsia." (PMID 39318551, 2024). "By integrating our previous data on DNA methylation from preeclamptic placental tissues, we identified that the ANKRD37 and PFKFB3 genes may contribute to the pathogenesis of preeclampsia through DNA methylation‐mediated transcriptome expression under hypoxic conditions." (PMID 38899809, 2024). "Our study verified that the TLR4/NF-κB/PFKFB3 signaling might be a novel link between the reprogrammed glycometabolism and trophoblastic pyroptosis, providing novel insights into the pathogenesis of preeclampsia." (PMID 34804360, 2021). "In this study, we observed that ANKRD37 and PFKFB3 exhibited hypomethylation and high expression in HTR‐8/SVneo cells after hypoxia, and they also showed low methylation in preeclampsia placental tissues." (PMID 38899809, 2024). "We also previously demonstrated the role of the MALAT1/miR-26/PFKFB3 axis in the pathogenesis of early-onset preeclampsia (EOPE) and proposed that targeting PFKFB3 to drive glycolysis is a promising therapeutic strategy for EOPE." (PMID 36354563, 2022). "A recent study has found that inhibition of the trophoblast TLR4/NF-κB/PFKFB3 signaling pathway to correct glycometabolic reprogramming and NLRP3 inflammation-induced pyroptosis may be a treatment approach for preeclampsia." (PMID 36589684, 2022).
rectal cancer (6 papers, 2021 to 2025). A primary or metastatic malignant neoplasm that affects the rectum. "The key transcriptional difference between monocytes of patients with colon and rectal cancer was increased expression of PFKFB3, activator of glycolysis that is currently considered as therapy target for major solid cancers." (PMID 36733385, 2022). "We next asked whether PFKFB3 expression would affect disease-free and overall survival rates of colon and rectal cancer patients, respectively." (PMID 33671096, 2021). "The finding that PFKFB3 expression is significantly increased in both colon and rectal carcinoma confirms our hypothesis that a metabolic shift towards glycolysis happens during colon- and rectal-carcinogenesis, and that indeed its increased expression affects patients’ outcomes." (PMID 33671096, 2021). "We have recently identified that expression of the stimulator of glycolysis PFKFB3 is elevated in monocytes of patients with colon but no rectal cancer." (PMID 41516095, 2025). "PFKFB3+ monocyte-derived macrophages massively infiltrated tumor in the colon, and Nanostring spatial profiling identified a correlation of PFKFB3 with tumor-promoting properties of TAMs in colon but not in rectal cancer." (PMID 37628978, 2023). "Monocyte-expressed PFKFB3 was indicative for tumor relapse specifically in colon but not rectal cancer." (PMID 37628978, 2023). "Nanostring technology identified correlation of PFKFB3 with amount and tumor-promoting properties of TAMs in colon but not in rectal cancer." (PMID 36733385, 2022). "In rectal cancer, correlation of PFKFB3 expression with CD14, but not with M2-like markers was found." (PMID 36733385, 2022). "Finally, we showed that PFKFB3 expression is a significant prognostic factor for poor OS and DFS and for high risk of tumor relapse in colon but not rectal cancer patients." (PMID 36733385, 2022).
fibrosis (5 papers, 2023 to 2025). the formation of excess fibrous connective tissue in an organ or tissue in a reparative or reactive process. "Collectively, these data indicated that SPARC, p38γ, and PFKFB3 were upregulated in the skin of BLM-induced fibrosis model in C57BL/6 mice." (PMID 39482755, 2024). "Consistently, silencing Pfkfb3 decreased collagen accumulation and attenuated cardiac fibrosis and preserved cardiac functions of post-MI mice." (PMID 37162556, 2023). "Together, these results suggested that PFKFB3 may play a role in CFs following MI, further influencing cardiac fibrosis and adverse remodeling." (PMID 37509108, 2023). "In addition, the upregulation of SPARC, p38γ, and PFKFB3 were discovered in the skin of BLM-induced fibrosis mice model, and the inhibition of p38γ and PFKFB3 could relieve BLM-induced skin fibrosis." (PMID 39482755, 2024). "In addition, in BLM-induced fibrosis mice, inhibition of p38γ and PFKFB3 relieved skin fibrosis." (PMID 39482755, 2024). "SPARC, p38γ, and PFKFB3 were highly expressed in patients with keloid and BLM-induced fibrosis mice." (PMID 39482755, 2024). "The expression of SPARC, p38γ, 6-phosphofructo-2-kinase/fructose-2,6-biphosphatase 3 (PFKFB3), α-SMA, and Ki67 in patients with keloid and bleomycin (BLM)-induced fibrosis mice was assessed utilizing western blot, qRT-PCR, and immunohistochemical staining." (PMID 39482755, 2024). "These insights highlight ALA’s therapeutic potential by inhibiting lung fibroblast activation via TGF-β1 and autophagy proteins (Parkin/LC3) while counteracting metabolic reprogramming in bleomycin-induced fibrosis by suppressing HK2, PFKFB3, Parkin, and LC3 activation." (PMID 40868211, 2025). "Notably, 3PO reduced PFKFB3 expression and inhibited the transforming growth factor-beta 1/mothers against the decapentaplegic homolog 2/3 (TGF-β1/SMAD2/3) signaling pathway to inhibit cardiac fibrosis after MI." (PMID 37509108, 2023).
Hepatic steatosis (5 papers, 2020 to 2021). Steatosis is a term used to denote lipid accumulation within hepatocytes. "In this model, the group found that indole treatment significantly alleviated hepatic steatosis and inflammation via the master regulatory gene of glycolysis, 6-phosphofructo-2-kinase/fructose-2,6-biphosphatase 3 (PFKFB3)." (PMID 34685614, 2021). "It was previously shown that adipose tissue-specific PFKFB3-overexpression in mice significantly increased liver weight, hepatic steatosis, and hepatic expression of lipogenesis genes such as ACC1, FAS, and SREBP1c." (PMID 34943809, 2021). "Clearly, PFKFB3 signifies how adipose tissue plays an essential role in regulating hepatic steatosis and liver inflammation, two key aspects of NAFLD/NASH." (PMID 34943809, 2021). "The role of PFKFB3 in NAFLD was further demonstrated by the disruption of the myeloid PFKFB3 that resulted in more severe hepatic steatosis and inflammation." (PMID 32717871, 2020). "For instance, adipocyte-selective overexpression of PFKFB3/iPFK2, which activates 6-phosphofructo-1-kinase (6PFK1) to enhance glycolysis, decreased HFD-induced liver proinflammatory response and improved insulin signaling; although leading to increased hepatic steatosis." (PMID 36994336, 2021).
liver cancer (5 papers, 2021 to 2023). An epithelial or non-epithelial malignant neoplasm that arises from the liver. "The combination of PFKFB3 inhibitor and Sorafenib has been demonstrated to have a synergistic effect on the treatment of liver cancer, consistent with the present study findings." (PMID 36990998, 2023). "PFKFB3 was expressed in liver cancer cells and liver cells, while PFKFB3 was significantly upregulated in liver cancer cells." (PMID 37476196, 2023). "PFKFB3, the key factor in the Warburg effect, was overexpressed in liver cancer, and the regulation of IL-6/HIF-1α/PFKFB3 played an important role in dosage-specific pro-invasive effect of sorafenib." (PMID 37476196, 2023). "PFKFB3 not only contributes to the proliferation, metastasis, and angiogenesis of cancer but also induces the resistance of liver cancer cells to sorafenib through the PFKFB3/HIF-1A positive feedback loop." (PMID 34540667, 2021).
myocardial infarction (5 papers, 2021 to 2025). Gross necrosis of the myocardium, as a result of interruption of the blood supply to the area, as in coronary thrombosis. "Meeting all the cutoff criteria across all the data set analyzed, MAN2A2/TNFRSF12A/SPP1/CSNK1D/PLAUR/PFKFB3/CXCL16 (herein we termed it MTSCPPC signature) was identified as a novel pathological signature of myocardial infarction and was used for subsequent analyses." (PMID 35163208, 2022). "In this study, silybin was shown to alleviate post-myocardial infarction heart failure by downregulating HIF-1α expression and inhibiting its nuclear translocation, which, in turn, reduces the HIF-1α-mediated upregulation of key glycolytic enzymes (PFKFB3, GLUT1, LDHA)." (PMID 40944191, 2025).
renal cell carcinoma (5 papers, 2021 to 2024). "Cytoplasmic PFKFB3 was found to strongly promote ATP generation, thereby inhibiting autophagy in renal cell carcinoma (RCC) cells, while nuclear PFKFB3 was associated with autophagy-promoting properties of the same cell line." (PMID 33671514, 2021). "Apart from glycolysis, PFKFB3 is also known to stimulate cell proliferation in cancer cells as revealed by the knockdown of PFKFB3 which suppressed both glycolysis and cell-cycle G1/S progression in renal cell carcinoma cell lines." (PMID 39342193, 2024). "Regulates glycolysis by improving PFKFB3 expression in renal cell carcinoma cells." (PMID 38390324, 2024). "In renal cell carcinoma, PFKFB3 knockout inhibits glycolysis and cell proliferation, suggesting that PFKFB3 could be used as a potential therapeutic target." (PMID 35957825, 2022). "However, the specific function and clinical significance of PFKFB3 in renal cell carcinoma (RCC) are yet not clarified." (PMID 35057732, 2022).
tongue cancer (5 papers, 2016 to 2021). A malignant neoplasm affecting the tongue. "The expression of the key glycolytic enzyme PFKFB3 at the mRNA and protein level in tongue cancer cells shows circadian oscillations controlled by the transcription factor CLOCK." (PMID 34948470, 2021). "The study with tongue cancer cells confirms that PFKFB3 inhibition at its peak levels significantly decreases cell proliferation and lactate production." (PMID 34948470, 2021). "PFKFB3 inhibition significantly retarded the growth of implanted human tongue cancer cell in mice only at certain time points within the circadian cycle." (PMID 29263928, 2017). "In patients with tongue cancers, PFKFB3 expression in both cancers and its surrounding tissues was increased significantly compared with that in the control, and was accompanied with dys-regulated expression of core circadian genes." (PMID 27079271, 2016). "The present study examined PFKFB3 expression in human tongue cancer tissues at both protein and mRNA levels." (PMID 27079271, 2016). "In relative to control KC cells, human tongue cancer SCC9 cells displayed a different pattern of rhythmic PFKFB3 expression, which was characterized by a mid-phase peak in PFKFB3 expression." (PMID 27079271, 2016). "In the in vitro systems, SCC9 tongue cancer cells displayed rhythmic expression of PFKFB3 and CLOCK that was distinct from control KC cells." (PMID 27079271, 2016). "PFKFB3 transcription has also been found to be rhythmically associated with the circadian cycle, as CLOCK transcription factor binds to the PFKFB3 E-box promoter Diminished tongue cancer growth in vivo was evident with PFKFB3 inhibition only at certain circadian time points." (PMID 34831136, 2021). "PFKFB3 expression was increased at both the mRNA and protein levels in human tongue cancers." (PMID 27079271, 2016). "The present study investigated the link between circadian clock dysregulation and PFKFB3 expression in human tongue cancer and tongue cancerous cells, and demonstrated a critical role for PFKFB3 in controlling tongue cancer by responding to circadian clock outputs." (PMID 27079271, 2016). "Considering this, cultured tongue cancer cells and control cells were synchronized and used to confirm the relationship between BMAL1/CLOCK and PFKFB3." (PMID 27079271, 2016). "Additionally, PFKFB3 shows circadian expression at mRNA and protein level, which is controlled predominantly by transcription factor CLOCK, as shown in tongue cancer cell line." (PMID 33922320, 2021). "However, the down-regulation of BMAL1 and CLOCK expression and the up-regulation of PFKFB3 expression in tongue cancer samples do not necessarily imply that BMAL1 and/or CLOCK down-regulation leads to increased PFKFB3 expression." (PMID 27079271, 2016).
astrocytoma (4 papers, 2017 to 2022). "This study revealed that PFKFB3 splice variant UBI2K4 was down-regulated within high-grade astrocytoma, in comparison to low-grade astrocytoma and non-neoplastic brain tissue." (PMID 35057732, 2022). "Increased expression levels of total PFKFB3 in high-grade astrocytomas compared to low-grade astrocytomas and non-neoplastic brain tissue were found." (PMID 34234350, 2021).
cervical cancer (4 papers, 2021 to 2023). A primary or metastatic malignant neoplasm involving the cervix. "More recent studies have shown the involvement of cytoplasmic PFKFB3 in response to DNA-damaging cisplatin in cervical cancer cells and UV damage in primary mouse embryonic fibroblast." (PMID 34298817, 2021). "Cisplatin has been reported to promote glycolysis via triggering cytoplasmic localization of PFKFB3 in a cervical cancer cell line." (PMID 34298817, 2021).
heart failure (4 papers, 2021 to 2025). Inability of the heart to pump blood at an adequate rate to meet tissue metabolic requirements. "Deleting endothelial sirtuin 3 reduces GLUT1 and PFKFB3 expressions, leading to heart failure in a myocardial ischemia model and pressure overload-induced heart failure rodent models." (PMID 33850277, 2022). "Here, we demonstrate that in NHPs, amylin deposition in heart failure (HF) contributes to cardiac dysfunction via activation of HIF1α and PFKFB3 signaling." (PMID 33580152, 2021). "Future approaches may involve guiding treatment selection based on metabolic subtypes, such as PFKFB3 inhibitors for glycolysis-dominant heart failure patients or CPT1 agonists for those with lipid metabolism abnormalities." (PMID 41403700, 2025). "For example, glycolysis-dominant heart failure patients may benefit from PFKFB3 inhibitors, while those with lipid metabolism abnormalities may be more suitable for CPT1 agonists." (PMID 41403700, 2025). "The present study shows that SIL exerts cardioprotective effects by modulating the HIF-1α-glycolytic pathway, leading to the downregulation of key glycolytic enzymes (GLUT1, PFKFB3, LDHA) and the restoration of metabolic homeostasis in heart failure." (PMID 40944191, 2025).
lung adenocarcinoma (4 papers, 2014 to 2023). A carcinoma that arises from the lung and is characterized by the presence of malignant glandular epithelial cells. "Moreover, blocking PFKFB3 activity with PFK15 resulted in a significant reduction in cyclin D1 expression in tumor cells isolated from lung adenocarcinoma after 24 h." (PMID 33922320, 2021). "We examined serial sections of human H460 lung adenocarcinoma xenograft tumors resected from athymic mice for expression of PFKFB4 and PFKFB3 and correlated the expression levels of these proteins using carbonic anhydrase IX, a potent transcriptional target of HIF-1α, as a hypoxia marker." (PMID 25115398, 2014). "Although the differences in metabolic functions of PFKFB3 and PFKFB4 are poorly understood, we observed a more robust induction of PFKFB4 protein relative upon exposure of H460 cells to 1% oxygen and significant correlation between hypoxia and PFKFB4 expression in lung adenocarcinoma tissues." (PMID 25115398, 2014).
Myeloma (4 papers, 2021 to 2024). "Analysis of correlation between KDM2A or PFKFB3 protein levels and clinicopathological parameters of multiple myeloma patients." (PMID 34079757, 2021). "Our data demonstrates that in myeloma cells KDM2A interacts with PFKFB3 and mediates its ubiquitination-induced degradation." (PMID 34079757, 2021). "Myeloma cells secreted IL-32γ-containing exosomes, which upregulated the expression of PD-L1 on macrophages by increasing the expression of 6-phosphofructo-2-kinase/fructose-2,6-bisphosphatase 3 (PFKFB3), ultimately facilitating immune evasion." (PMID 37313405, 2023). "This study is the first to report PFKFB3 can be ubiquitylated by KDM2A in multiple myeloma." (PMID 34079757, 2021). "Our findings further suggest that regulating KDM2A-mediated PFKFB3 ubiquitination may be a promising application in multiple myeloma treatment." (PMID 34079757, 2021). "Treatments with the PFKFB3 inhibitor, PFK158, and PFKFB4 inhibitor, 5MPN, were found to inhibit the growth of myeloma cells." (PMID 35578370, 2022). "Our data also suggest that administration of PFKFB3 and PFKFB4 inhibitors may be a powerful strategy against myeloma cells and to enhance the cytotoxic effects of proteasome inhibitors in hypoxic conditions." (PMID 35578370, 2022).
oral squamous cell carcinoma (4 papers, 2021 to 2022). "PFKFB3 expression in oral squamous cell carcinoma is notably increased and correlated with the differentiation degree and tumor size." (PMID 34612136, 2021). "The positive correlation between PFKFB3 and CD163, CD31 suggested that PFKFB3 possibly promoted angiogenesis through modulating the infiltration of CD163 + tumor-associated macrophages (TAMs) in oral squamous cell carcinoma." (PMID 35784750, 2022). "According to another hypothesis, PFKFB3 may facilitate angiogenesis in oral squamous cell carcinoma by regulating the infiltration of CD163+ tumor-associated macrophages (TAMs), as the expression of PFKFB3 was correlated with CD163 and CD31." (PMID 33671514, 2021). "PFKFB3 may promote tumor progression and angiogenesis during metastasis by regulating the infiltration of CD163+ TAMs in oral squamous cell carcinoma." (PMID 34612136, 2021).